GFAP (glial fibrillary acidic protein)
Diseases named in the same sentence as GFAP in open-access papers (continued):
Sharing a sentence is not in itself a finding about the gene and the disease.
autoimmune disease of the nervous system (7 papers, 2018 to 2025). "GFAP astrocytic disease is an autoimmune disorder of the nervous system with a low incidence rate, and its etiology, pathology, and mechanism are not yet fully understood." (PMID 37781407, 2023). "Autoimmune glial fibrillary acidic protein (GFAP) astrocytopathy, first defined in 2016, is an autoimmune disease of the nervous system, with presence of GFAP immunoglobulin G (IgG) in the serum or cerebrospinal fluid (CSF) as a specific biomarker." (PMID 36782173, 2023). "Autoimmune glial fibrillary acidic protein (GFAP) astrocytopathy is an autoimmune disease of the nervous system first defined in 2016." (PMID 30568655, 2018). "Autoimmune glial fibrillary acidic protein (GFAP) astrocytopathy is an autoimmune nervous system disorder established only in 2016 that involves the presence of GFAP autoantibodies, particularly IgG targeting GFAPα, detected in both cerebrospinal fluid (CSF) and serum of affected individuals." (PMID 39328614, 2024). "Glial fibrillary acidic protein (GFAP) astrocytopathy, a novel autoimmune disease of the nervous system, was first defined in 2016." (PMID 36805663, 2023).
brain edema (7 papers, 2014 to 2023). Increased intracellular or extracellular fluid in brain tissue. "In conclusion, our findings revealed altered levels of TNFα, Kir 4.1, GFAP, and AQP4 in HE-associated brain edema." (PMID 36060277, 2022). "GFAP is astrocytic cytoskeletal element and a major contributor of astrocytic reactivity, and abnormal expression of GFAP occurs in neuroinflammation and brain edema-eliciting diseases." (PMID 34975411, 2021). "Our data show that piperine treatment can reduce the degree of cerebral edema, down-regulate TNF-α, IL-1β, and BDNF, decrease the reactivity of GFAP in the hippocampus, and inhibit TBI-induced seizures." (PMID 32655468, 2020). "Thus, the expression of glial fibrillary acidic protein (GFAP), a marker of reactive astrogliosis, in the ischemic region is positively correlated with the severity of cerebral edema." (PMID 33298024, 2020).
cerebral amyloid angiopathy (7 papers, 2021 to 2025). "Cerebral GFAP is a central marker of AD: higher levels of GFAP in cortical gene and protein expression are associated with increased β-amyloid pathology, cerebral amyloid angiopathy, and faster cognitive decline, particularly in β-amyloid-positive individuals." (PMID 41465278, 2025). "Most prominently, elevated GFAP levels correlated with greater burden of cerebral amyloid angiopathy (CAA), which is intuitive given the strong associations of GFAP expression and global amyloid." (PMID 39580758, 2024). "Furthermore, we tested for associations between GFAP and numerous non-AD pathologies, including infarcts, cerebral amyloid angiopathy, TDP-43, and Lewy bodies." (PMID 39580758, 2024). "Reactive astrocytes were also found surrounding fibrillar plaques and were prominent around the vascular amyloid such that glial fibrillary acidic protein (GFAP) immunostaining could be used as a surrogate for cerebral amyloid angiopathy (CAA) at all ages examined." (PMID 35394029, 2022). "To investigate the effects of targeted knockdown of transforming growth factor-beta receptor II (TGF-PR2) in cerebral amyloid angiopathy (CAA) mice, we conducted immunohistochemical analyses focusing on TGF-βR2 and glial fibrillary acidic protein (GFAP) expressions." (PMID 38854014, 2024).
chronic kidney disease (7 papers, 2023 to 2026). Impairment of the renal function secondary to chronic kidney damage persisting for three or more months. "Body mass index was negatively associated with GFAP and NfL, and chronic kidney disease with higher levels of all biomarkers." (PMID 39350363, 2024). "In analyses stratified by IL‐6 levels, the association between chronic kidney disease and concentration of NfL, t‐tau, and GFAP was stronger in participants with high levels of IL‐6 than in those with low IL‐6." (PMID 38717935, 2024). "Additionally, chronic kidney disease was associated with elevated levels of p‐tau181, t‐tau, NfL, and GFAP." (PMID 38717935, 2024). "Looking at specific disease combinations, the concentrations of p‐tau181, t‐tau, NfL, and GFAP were even further elevated when two among chronic kidney disease, anemia, and heart diseases co‐occurred in the same person." (PMID 38717935, 2024). "Nonetheless, given the high prevalence of chronic kidney disease in the general population, especially in the elderly, further studies are required to clarify the influence of renal function on plasma GFAP levels and their clinicopathological correlates." (PMID 37762278, 2023).
Crohn disease (7 papers, 2011 to 2025). A gastrointestinal disorder characterized by chronic inflammation involving all layers of the intestinal wall, noncaseating granulomas affecting the intestinal wall and regional lymph nodes, and transmural fibrosis. "Although the GDNF and GFAP content are increased in Crohn's disease (CD), it is significantly less." (PMID 21235736, 2011). "In an animal model of Crohn's disease, the glial network was impaired in noninflamed regions of the intestinal mucosa, which was reflected in a significant decrease in GFAP immunoreactivity." (PMID 24790767, 2014).
demyelination (7 papers, 2013 to 2023). "Analysis of immunostaining data indicated that the intensity of GFAP fluorescent signals was increased on Days 6 and 7 after the induced demyelination model using lysolecithin compared with the intact group." (PMID 38107502, 2023). "Although being significantly elevated with onset and progression of cerebral involvement in CCALD patients, GFAP had lower discriminative capability for CALD-indicative demyelination than NfL." (PMID 37683329, 2023). "In the present study we have investigated the modulatory role of TRPA1 receptors expressed by GFAP positive cells in the cuprizone-induced demyelination model using mGFAP-driven conditional TRPA1 receptor knockout mice." (PMID 31905673, 2019). "Although the densities of the GFAP+ cells gradually increased in the corpus callosum and cortex during the course of cuprizone-induced demyelination, a significant proportion of the GFAP+ cells were TSPO-negative in the control and cuprizone-exposed mice." (PMID 30696113, 2019). "Has immunological demyelination simply slowed the astrocyte response, killed a percentage of astrocytes, or even metabolically damaged them so as to decrease their ability to generate GFAP?" (PMID 24319469, 2013). "The main goal of this research was to assess the neuroprotective effects of IVM and nano-IVM in CPZ-induced demyelination mice and to observe the role of the TRPA1/NF-kB/GFAP signaling pathway." (PMID 37886003, 2023).
HIV-1 infection (7 papers, 2017 to 2024). The type species of lentivirus and the etiologic agent of acquired immunodeficiency syndrome (AIDS). "Our observation of increased GFAP expression in HIV-1 infected neurospheres is consistent with previous literature that has characterized HIV-1 infection by astrocytosis." (PMID 35132117, 2022). "We assessed by flow cytometry the intracellular glial fibrillary acidic protein (GFAP) expression, a common marker of astrogliosis, by astrocytes following either HIV-1 infection or treatment with LRA." (PMID 29228979, 2017). "Systemic HIV-1 infection of dual humanized animals increased the influx of human macrophages and affected the number of hu-GFAP-expressing cells." (PMID 29084769, 2017). "HIV-1 infection reduced the expression of human GFAP (FPKM log2 changes -0.55, P=0.033)." (PMID 29084769, 2017). "The glial fibrillary acidic protein (GFAP), which is used as a marker for reactive astrocytes, increases during HIV-1 infection and has helped identify astrocytes as a significant viral reservoir in the brain." (PMID 31829243, 2019). "Our results indicate that GFAP expression by astrocytes is neither affected by HIV-1 infection nor by a treatment with the tested LRA (data not shown)." (PMID 29228979, 2017).
hypoxic-ischemic encephalopathy (7 papers, 2015 to 2025). "In another study, GFAP assays were used to detect glial cell damage in the brain and indicate hypoxic-ischemic encephalopathy." (PMID 36340713, 2022). "GFAP has been shown to be a useful biomarker in the diagnosis and prognosis of neonatal hypoxic-ischemic encephalopathy." (PMID 36428450, 2022). "Brain-specific glial fibrillary acidic protein (GFAP) has been suggested as a potential biomarker for hypoxic ischemic encephalopathy (HIE) in newborns." (PMID 26733938, 2015). "Elevated GFAP levels in cord serum correlate with the severity of hypoxic-ischemic encephalopathy." (PMID 36340713, 2022). "High serum GFAP concentrations have been reported in infants with hypoxic-ischemic encephalopathy." (PMID 36428450, 2022). "Especially, patients with NFL or GFAP levels within the normal range do not have hypoxic-ischemic encephalopathy (HIE) with a very high probability." (PMID 36927495, 2023).
metastatic carcinoma (7 papers, 2008 to 2026). A carcinoma which has spread from the original site of growth to another anatomic site. "A combination of immunostains, including GFAP and cytokeratin CAM5.2, has been suggested as useful in differentiating poorly differentiated metastatic carcinoma from GBM." (PMID 18624795, 2009). "Although, metastatic carcinomas are positive for cytokeratins, these are consistently negative for GFAP." (PMID 18928567, 2008). "The recommended panel should include Cytokeratins (positive in MPE, metastatic carcinoma and chordoma), GFAP (positive in MPE and negative in metastatic carcinoma and chordoma), and S-100 protein (positive in MPE, chordoma but negative in most metastatic carcinomas)." (PMID 18928567, 2008).
migraine (7 papers, 2017 to 2025). "Correlation analysis between NfL, GFAP, age at sampling, migraine course, migraine frequency, days from last attack, and attack severity showed an association between NfL and age at sampling (rho 0.643, p < 0.001) and NfL and migraine course (rho 0.519, p < 0.001)." (PMID 40781571, 2025). "The potential role of GFAP, a well-recognized biomarker of astrocytic damage, was recently investigated in migraine with diverging results." (PMID 40781571, 2025). "The aim of this study was to assess axonal and glial damage measuring serum levels of neurofilament light chain (NfL) and glial fibrillary acidic protein (GFAP) in migraine patients." (PMID 40781571, 2025). "GFAP levels are significantly higher in migraine patients (103.15 pg/mL [IQR 70.98–146.34] vs. 69.43 pg/mL [IQR 53.04–91.85], p < 0.001), without significant difference between EM and CM patients and between patients with and without an attack at sampling (p = 0.235)." (PMID 40781571, 2025). "Attack at sampling/days from last attack, migraine frequency/attack severity did not influence NfL or GFAP levels." (PMID 40781571, 2025). "In line, the absence of an increase in GFAP in migraine patients, as well as the lack of an increase in NFL speaks against astrocytic or neuroaxonal damage in the CNS in migraine patients." (PMID 38561692, 2024). "The absence of correlation between attack stage/frequency might be related to the kinetics of GFAP, which is not completely understood, and might reflect the chronic rather than acute relation of migraine with astrocytic involvement." (PMID 40781571, 2025). "Regardless of why t-Tau protein elevation occurs in migraine patients, the lack of difference in concentrations of other biomarkers of neuroaxonal degeneration such as NfL, GFAP and UCHL1 needs to be emphasized and refutes major neurodegenerative processes in migraine." (PMID 38561692, 2024). "In the acute migraine model, NTG administration induced microglial and astroglial activation in the TNC area that was detectable as an increased number of clusters of differentiation molecule 11b (CD11b)— and glial fibrillary acidic protein (GFAP)-positive cells when compared with the CT group." (PMID 36430567, 2022). "NfL, GFAP, and UCH-L1 were not different from controls and interictal migraine patients." (PMID 37726712, 2023).
myopia (7 papers, 2013 to 2025). "Greater degrees of myopia and vitreous elongation were associated with reduced peripapillary RGCs and astrocyte density, and increased GFAP expression and intensity." (PMID 39769248, 2024). "The decrease in astrocytes in the parafovea concurrently shows an increase in GFAP spatial coverage that is significantly greater in the older myopes that have experienced myopia for longer." (PMID 38607034, 2024). "Myopic changes in astrocyte density, GFAP+ spatial coverage and inner retinal layer thicknesses suggest astrocyte template reorganization during myopia development and progression which increased over time." (PMID 38607034, 2024). "Supporting the existence of retinal glia alterations in myopia, increased GFAP expression and both astrocyte and Müller cell morphology changes have been demonstrated in a mouse model of myopia." (PMID 38607034, 2024). "Myopia’s effect on the astrocyte, GFAP+ template, and inner retinal thicknesses was greater in marmosets induced with myopia for 10 months compared to those induced for 4 months." (PMID 38607034, 2024). "In a marmoset model of myopia, myopic eyes showed a smaller number of astrocytes yet higher expression of GFAP, consistent with astrogliosis." (PMID 39759766, 2024). "Patients with myopia (> −0.5 dpt) had significant higher median vitreous body GFAP levels (50 ng/mL) compared to those with hyperopia (20 pg/mL, p = 0.024)." (PMID 26279003, 2015). "In patients with proliferative diabetic retinopathy or myopia, the immunoreactivity of bFGF co-localized to glial fibrillary acidic protein (GFAP)-positive cells in surgically excised retinal tissues." (PMID 23861940, 2013). "In addition, increased GFAP expression from astrocytes and Müller cells has recently been identified in a mouse model of myopia." (PMID 40141465, 2025). "We hypothesize that the increase in GFAP expression and intensity observed in this study may be indicative of neuroprotective astrocyte activity in the early stages of myopia development." (PMID 39769248, 2024). "GFAP levels in the vitreous were also elevated in cases of myopia." (PMID 26279003, 2015). "Marmosets induced with myopia for six months developed axial myopia, had a thinner ppRNFL, reduced peripapillary ganglion cell (≈20%) and astrocyte density (≈42%), increased panretinal GFAP expression (≈42%) and nasal mid-periphery staining intensity (≈81%) compared to age-matched controls." (PMID 39769248, 2024). "Interestingly, mice induced with form deprivation myopia also exhibit an increased GFAP reactivity that may translate into increased foveal vulnerability and subsequent changes to central retinal health in progressive myopia." (PMID 38607034, 2024). "The results of this study show that experiencing myopia for longer exacerbates the decreased astrocyte density and increased GFAP+ spatial coverage seen in a progressive model of non-human primate myopia." (PMID 38607034, 2024). "Previous work from our lab has described a decrease in astrocyte density along with increased glial fibrillary acidic protein (GFAP) spatial coverage in myopic marmoset eyes (Callithrix jacchus), an established non-human primate model of myopia." (PMID 38607034, 2024).
vascular dementia (7 papers, 2015 to 2025). A degenerative vascular disorder affecting the brain. "Next, we look at the connections between GFAP and Vascular Dementia (VD)." (PMID 40832351, 2025).
bone cancer (6 papers, 2014 to 2024). A primary or metastatic malignant neoplasm affecting the bone or articular cartilage. "The spinal levels of IL-17, CXCL1 and GFAP were also measured to evaluate if these proinflammatory molecules were implicated in RvD2 anti-nociception in bone cancer pain." (PMID 36672133, 2023). "TCI causes neurochemical alterations such as c-Fos, GFAP and IBA1 in the ipsilateral DH, in addition to behavioral changes of bone cancer." (PMID 24735601, 2014). "In addition to activating the neurological secretion of opioid substances, electroacupuncture acts synergistically with endogenous opioids to inhibit astrocyte activation by suppressing spinal glial fibrillary acidic protein (GFAP) expression, thereby reducing bone cancer pain in rats." (PMID 37255718, 2023). "However, GFAP was not activated until day 7, suggesting that CXCL12 may be also produced and released from other cells in the early phase of bone cancer." (PMID 24735601, 2014).
cerebral small vessel disease (6 papers, 2022 to 2026). Cerebral small vessel disease is the term currently used to pathological processes that affect the brain parenchymal circulation (arterioles, capillaries, and veins). "Neurofilament light chain (NfL) and glial fibrillary acidic protein (GFAP) have emerged as biomarkers for cerebral small vessel disease (SVD)." (PMID 38581544, 2024). "Serum glial fibrillary acidic protein (sGFAP) has been proposed as a biomarker in various neurological diseases but has not yet been systematically investigated in patients with cerebral small vessel disease (CSVD)." (PMID 36056929, 2023).
Cirrhosis (6 papers, 2014 to 2025). A chronic disorder of the liver in which liver tissue becomes scarred and is partially replaced by regenerative nodules and fibrotic tissue resulting in loss of liver function. "Of particular relevance to the current study, a recent report found that serum GFAP was increased in patients with hepatic encephalopathy associated with cirrhosis." (PMID 38606159, 2024). "A recent study showed elevated GFAP in the blood of patients with hepatic encephalopathy associated with cirrhosis, which was correlated with ammonia and IL6 levels in serum." (PMID 38606159, 2024). "Although astrocyte activation has been described in experimental cirrhosis, the specific age-contributing role in increased number of GFAP-positive astrocytes has also been reported, supporting results presented herein." (PMID 39656486, 2024). "Bergmann glial fibers stained with GFAP present a disorganized, damaged and hypertrophied morphology in all groups of patients with steatohepatitis, cirrhosis and HE compared to controls, who show thin and intact morphology." (PMID 29445232, 2018). "The use of GFAP may help treat CHC patients at a stage when fibrotic changes are mild because once end-stage cirrhosis establishes, liver transplantation is the sole modality of treatment." (PMID 25225520, 2014). "Recently, glial fibrillary acidic protein (GFAP), an intermediate filament found in astrocytes, and especially neurofilament light chains (NfL), an important structural protein found in neurons, have emerged as promising biomarkers for HE in patients with cirrhosis." (PMID 41200277, 2025). "Therefore, the aim of this study was (i) to assess whether NfL and GFAP serum levels are associated with the development of post‐TIPS HE and, (ii) to investigate the course of NfL and GFAP levels in patients with cirrhosis after TIPS." (PMID 41200277, 2025). "Microglial and glial activation are usually associated with cirrhosis-related neuro-inflammation but in vagotomized mice, the expression of GFAP and IBA were abrogated even with cirrhosis." (PMID 34248683, 2021).